SLC5A3 (solute carrier family 5 member 3)
Diseases named in the same sentence as SLC5A3 in open-access papers (continued):
Sharing a sentence is not in itself a finding about the gene and the disease.
neuroblastoma (1 paper, 2023). Neuroblastoma (NB) is the most common solid, extracranial childhood tumor. "Long non-coding RNA NORAD upregulated SLC5A3 expression by sponging microRNA-204-5p and consequently alleviates oxidative injury and suppressed cell death in neuroblastoma cells." (PMID 37324953, 2023).
osteosarcoma (1 paper, 2022). A usually aggressive malignant bone-forming mesenchymal neoplasm, predominantly affecting adolescents and young adults. "The expression of BNIP3, SLC38A5, CKMT2, CXCL11, SLC5A3, S100A3, and PGM1 genes was verified in osteosarcoma cells (Saos-2 and 143B) and normal osteoblasts (hFOB1.19)." (PMID 36578780, 2022).
pancreatic adenocarcinoma (1 paper, 2025). "Subsequently, we explored whether SLC5A3 overexpression is unique to pancreatic adenocarcinoma (PAAD) or observed in other cancer types." (PMID 40055335, 2025).
pancreatic cancer (1 paper, 2025). "Survival analysis of multiple patient cohorts, including TCGA–PAAD and SNU cohorts, revealed that high SLC5A3 expression was associated with significantly poor overall survival, highlighting its potential as a prognostic marker for pancreatic cancer." (PMID 40055335, 2025). "Although the oncogenic roles of SLC5A3 have been explored in different cancers, its specific functions and association with chemoresistance in pancreatic cancer remain unknown." (PMID 40055335, 2025). "To explore the effects of SLC5A3 depletion on tumor growth and mitochondrial function in gemcitabine-resistant pancreatic cancer, we used an orthotopic xenograft mouse model." (PMID 40055335, 2025). "Therefore, investigating the roles of SLC5A3 in chemoresistance will help to overcome chemoresistance in pancreatic cancer, thereby improving the patient outcomes." (PMID 40055335, 2025). "Therefore, strategies targeting SLC5A3 can be used as novel therapeutic approaches for gemcitabine-resistant pancreatic cancer by enhancing tumor suppression and alleviating mitochondrial dysfunction." (PMID 40055335, 2025). "We explored the biological effects of SLC5A3 KD on gemcitabine-resistant pancreatic cancer cells." (PMID 40055335, 2025). "This suggests that SLC5A3 contributes to the aggressive nature of pancreatic cancer." (PMID 40055335, 2025). "The similarities between the effects of SLC5A3 depletion and CCCP treatment emphasize the critical roles of mitochondrial dynamics in gemcitabine-resistant pancreatic cancer." (PMID 40055335, 2025).
pancreatic insulinoma (1 paper, 2023). An insulin-producing neuroendocrine tumor arising from the beta cells of the pancreas. "In this study, we show that MRPS6 but not SLC5A3 regulates glucose-stimulated insulin secretion (GSIS) in primary human β-cell and a mouse pancreatic insulinoma β-cell line." (PMID 37758822, 2023).
prediabetes (1 paper, 2022). "We identified that rs13052524 in MRPS6 and rs62212118 in SLC5A3 were associated with 2hPG in Hainan prediabetes (p = 4.35 × 10-6, p = 4.05 × 10-6, respectively)." (PMID 35299963, 2022). "In summary, we identified two novel SNPs (rs13052524 and rs62212118) in MRPS6/SLC5A3 that were associated with 2hPG in Hainan prediabetes." (PMID 35299963, 2022). "We found two susceptibility loci in MRPS6/SLC5A3 genes associated with 2hPG, six loci in LINC01648, MATN1, CRAT37, and SLCO3A1 genes associated with HbA1C, and five loci in TRPM3/TMEM2 and MLYCD/OSGIN1 correlated to BMI in Hainan prediabetes." (PMID 35299963, 2022).
respiratory failure (1 paper, 2021). The significant impairment of gas exchange within the lungs resulting in hypoxia, hypercarbia, or both, to the extent that organ tissue perfusion is severely compromised. "A consistent study revealed that SLC5A3-null mice, lacking SMIT1, die shortly after birth due to neurological dysfunctions and respiratory failure." (PMID 34202683, 2021).
thalassemia (1 paper, 2024). An inherited blood disorder characterized by a decreased synthesis of one of the polypeptide chains that form hemoglobin. "We found that the protein expression of SLC5A3 was significantly downregulated in HbH patients compared with normal controls without thalassemia." (PMID 39088431, 2024).
cancer (7 papers, 2018 to 2025). A tumor composed of atypical neoplastic, often pleomorphic cells that invade other tissues. "SLC5A3 plays key roles in cancer cell survival and proliferation via cellular osmoregulation and metabolic demand regulation." (PMID 40055335, 2025). "As a myo-inositol transporter, SLC5A3 regulates osmotic stress and cellular metabolism, particularly in cancer cells." (PMID 40055335, 2025). "To validate these findings, we used larger datasets from The Cancer Genomic Atlas (TCGA) and Genotype-Tissue Expression (GTEx) databases, which confirmed the significant upregulation of SLC5A3 levels in PAAD tumor tissues compared to those in normal tissues." (PMID 40055335, 2025). "Data from the GEPIA2 and Human Protein Atlas datasets showed that SLC5A3 levels were elevated in multiple cancer types, with the most significant overexpression observed in PAAD." (PMID 40055335, 2025). "SLC5A3 plays a key role in maintaining mitochondrial homeostasis, particularly in chemoresistant cancer cells, by preventing excessive mitophagy and preserving the mitochondrial integrity." (PMID 40055335, 2025). "Western blotting analysis results of all 20 sets of tissue lysates were combined, which revealed significant SLC5A3 protein upregulation in cancer tissues." (PMID 37324953, 2023). "Genes co-expressed with SLC5A3 were enriched in multiple signaling cascades involved in cancer progression." (PMID 37324953, 2023). "Kyoto Encyclopedia of Genes and Genomes analyses revealed that genes co-expressed with SLC5A3 were enriched in multiple pathways involved in cancer progression, including Hippo, FOXO, JAK-STAT, and extracellular matrix pathways." (PMID 37324953, 2023). "The protein levels of SLC5A3 were upregulated in the cancer tissue lysates prepared from four representative clinical specimens." (PMID 37324953, 2023). "The SLC5A3 mRNA levels in cancer tissues (“T”) were higher than those in healthy epithelial tissues (N”)." (PMID 37324953, 2023). "Conversely, in the primary lung epithelial cells (“pEpi”), ectopic overexpression of SLC5A3, using the described construct, failed to significantly increase CCK-8 viability and proliferation, again supporting a cancer cell specific effect by SLC5A3." (PMID 35760803, 2022). "Specifically, SLC family 5 member 3 (SLC5A3) is involved in several cancers." (PMID 40055335, 2025). "Some studies have examined the function of SLC5A3 in the pathogenesis of human cancer." (PMID 37324953, 2023). "In contrast, SLC5A3 overexpression promoted cancer cell proliferation and migration." (PMID 37324953, 2023). "SLC5A3 knockdown markedly inhibited the proliferation and in vitro migration of cancer cells." (PMID 37324953, 2023). "Moreover, SLC5A3 is a crucial regulator of cell response to osmotic stress, the latter plays an important role in regulating various signaling cascades and cancer cell progression, including cell migration, proliferation and DNA repair." (PMID 35760803, 2022). "Using our extensive pan-cancer NK cell atlas, we were able to generate a solely NK cell-derived, tissue-residency signature (atlas-TR: PSMA2, SLC5A3, CCL4L2, CLN3, SCGB1A1, AREG), which outperformed the conventional literature-derived TR signature across tissue and tumor type." (PMID 38956379, 2024).
tumor (6 papers, 2022 to 2025). "This provides additional insight into the potential mechanisms underlying the oncogenic effects of SLC5A3 in tumor cells." (PMID 40652057, 2025). "Patients with high SLC5A3 expression exhibited significantly short relapse-free survival, suggesting that elevated SLC5A3 expression is associated with gemcitabine resistance and tumor recurrence." (PMID 40055335, 2025). "Single-cell RNA sequencing (scRNA-seq) analysis identified the expression of MRGs in multiple cell types and found that SLC5A3 + malignant cells may mediate potential communication with tumor-associated fibroblasts through the PI3K-AKT pathway and cholesterol metabolism pathway." (PMID 40652057, 2025). "In vivo studies revealed that targeting SLC5A3 enhanced the efficacy of gemcitabine and significantly reduced the tumor growth." (PMID 40055335, 2025). "Based on the median expression of SLC5A3 in malignant cells, we classified them into SLC5A3 + tumor cells and SLC5A3- tumor cells." (PMID 40652057, 2025). "We found that in both metabolism-related pathways, SLC5A3 + tumor cells exhibit significant communication with CAFs, particularly through the FN1/SDC2, FGF7/FGFR1, NGF/SORT1, and LRPAP1/LRP1 receptor-ligand pairs." (PMID 40652057, 2025). "Among the analyzed SLC genes, levels of SLC5A3 were the most significantly upregulated in PDAC tumor tissues compared to those in the adjacent normal tissues." (PMID 40055335, 2025). "Collectively, these findings suggest that SLC5A3 plays multifaceted roles in PDAC progression by regulating the key processes essential for tumor growth and survival, underscoring the potential of targeting SLC5A3 as a novel therapeutic strategy." (PMID 40055335, 2025). "We found that compared to SLC5A3- tumor cells, SLC5A3 + tumor cells exhibited stronger interactions with CAFs, endothelial cells, and others." (PMID 40652057, 2025). "Further pathway enrichment analysis revealed that SLC5A3 + tumor cells exhibit higher activity in pathways related to cholesterol metabolism, the PI3K-Akt signaling pathway, and the TGF-β signaling pathway." (PMID 40652057, 2025). "In conclusion, our results suggest that SLC5A3 KD inhibits tumor growth by disrupting the mitochondrial function, inducing apoptosis, and arresting cell cycle progression." (PMID 40055335, 2025). "To investigate the function of SLC5A3 in the tumor microenvironment, we performed single-cell RNA sequencing analysis based on the GSE115978 dataset." (PMID 40652057, 2025). "The SLC5A3 mRNA expression levels in tumor tissues were markedly higher than those in paracancerous and healthy tissues (P < 0.05)." (PMID 37324953, 2023). "Results showed SLC5A3 protein upregulation in NSCLC tumor tissues of six representative patients (from Patient #1 to Patient #6)." (PMID 35760803, 2022). "When combining SLC5A3 blotting assay results of all 13 pairs of human tissues, we found that SLC5A3 protein expression in the NSCLC tumor tissues was significantly higher." (PMID 35760803, 2022). "The IHC results further confirmed SLC5A3 upregulation in NSCLC tumor tissues (Patient #1 and Patient #2)." (PMID 35760803, 2022). "As shown, the number of SLC5A3 transcripts in NSCLC tumor tissues (“Tumor”, n = 1037) was significantly higher than that in the normal lung tissues (“Normal”, n = 108)." (PMID 35760803, 2022). "Additionally, SLC5A3 expression is upregulated via TonEBP binding, contributing to tumor growth in cervical cancer." (PMID 40055335, 2025). "SLC5A3 mRNA and protein levels were consistently elevated in tumor tissues, suggesting that SLC5A3 may play a role in PDAC tumorigenesis." (PMID 40055335, 2025). "We found the SLC5A3 majorly expressed in the malignant cells which suggested it may be correlated with tumor progress." (PMID 40652057, 2025). "TonEBP knockdown suppressed SLC5A3 expression and inhibited pCCa-1 tumor growth in vivo." (PMID 37324953, 2023).
tumor (continued). "In addition, SLC5A3 mRNA expression was elevated in NSCLC tumor tissues (“Tumor”, n = 106), when compared to that in the paired adjacent normal lung tissues (“Normal”, n = 106)." (PMID 35760803, 2022). "The results of WB showed the SLC5A3 gene of SKCM cells (MV3) was silenced by siRNA and the tumor cells whose SLC5A3 gene was silenced had lower p-AKT expression levels." (PMID 40652057, 2025). "The harvested tumors and their corresponding weights showed that both SLC5A3 KD and CCCP treatment significantly reduced the tumor size and weight compared to those in the RES group." (PMID 40055335, 2025). "Furthermore, SLC5A3 was among the most upregulated genes in PDAC, as shown in the volcano plot comparing normal and tumor tissues, further confirming its role in PDAC progression." (PMID 40055335, 2025).
inflammatory myopathies (2 papers, 2018 to 2020). "Confirming our earlier descriptive myopathological results on SLC5A3, SLC6A6, and AKR1B1 expression, we found these factors upregulated in regenerating muscle fibers present in biopsies in this new cohort of inflammatory myopathy patients." (PMID 30364257, 2018). "SLC5A3 and SLC6A12 were expressed by inflammatory cells in inflammatory myopathy muscle biopsies." (PMID 30364257, 2018).
cardiac disease (1 paper, 2021). "In contrast to SGLT2, which is not present in the heart, two other members of the SLC5A gene family, namely SGLT1 (SLC5A1) and the sodium-myoinositol cotransporter-1 (SMIT1, SLC5A3) are expressed in the heart and have been shown to contribute to Na+ influx in cardiac disease." (PMID 34360742, 2021).
SLC5A3 also shares sentences with these, for which no sentence is quoted: Hyperglycemia (3 papers); bipolar disorder (2); glioblastoma (2); non-small cell lung carcinoma (2); Alzheimer’s dementia (1); cardiac hypertrophy (1); cardiovascular disease (1); coronary heart disease (1); diabetic ketoacidosis (1); diabetic neuropathy (1); Down syndrome (1); Duchenne muscular dystrophy (1); epilepsy (1); glaucoma (1); heart failure (1); Hypertension (1); hypertrophy (1); hypothyroidism (1); infection (1); iron overload (1); ischemic stroke (1); lung adenocarcinoma (1); myocardial infarction (1); nephrotic syndrome (1); Obesity (1); osteoarthritis (1); ovarian carcinoma (1).